TMA7 (translation machinery associated 7 homolog)
Synonyms: CCDC72; HSPC016
Tractability: PROTAC: ubiquitination databases record sites on it; its protein half-life has been measured.
Gene: Protein-coding gene on chromosome 3 (48,440,213 to 48,444,218, forward strand). Ensembl gene ENSG00000232112.
Subcellular location (Human Protein Atlas): Nucleoli; Nucleoli rim; Nuclear bodies; Nucleoplasm
Genetic constraint (gnomAD): Loss-of-function variants: 5 observed, 11.66 expected, observed/expected ratio (o/e) 0.43, 90% interval 0.22 to 0.9. The upper end of that interval is the gene's LOEUF score, 0.9, which puts it in group 3 of 6, group 1 being the genes least tolerant of losing a copy. Missense variants: 62 observed, 67.17 expected, observed/expected ratio (o/e) 0.92, 90% interval 0.75 to 1.14. Synonymous variants: 34 observed, 25.1 expected, observed/expected ratio (o/e) 1.35, 90% interval 1.03 to 1.78.
Homologues: Orthologues: chimpanzee TMA7 (100% identical), dog TMA7 (100% identical), macaque TMA7 (100% identical), mouse Tma7 (100% identical), pig TMA7 (100% identical), rat Tma7 (100% identical), guinea pig TMA7 (97% identical). Paralogues in human: TMA7B (89% identical).
Diseases named in the same sentence as TMA7 in open-access papers:
TMA7 is named in the same sentence as 5 diseases in open-access papers, as found by Europe PMC text mining. Sharing a sentence is not in itself a finding about the gene and the disease. The quoted sentences say what the papers report.
laryngeal squamous cell carcinoma (1 paper, 2025). A squamous cell carcinoma that arises from the larynx. "In laryngeal squamous cell carcinoma (LSCC), TMA7 deficiency increases autophagy, while IGF2BP3 prolongs TMA7 mRNA’s half-life, stabilizing it and activating the UBA2-PI3K pathway to inhibit autophagy." (PMID 40001550, 2025).
migraine (1 paper, 2023). "For kidney function, 19 significant tissue–gene pairs were found for migraine and eGFR using GTEx tissues, including four genes (TREX1, SHISA5, PRR13, TMA7) mainly expressed in tissues of the nervous and cardiovascular system." (PMID 37306871, 2023).
tumor (2 papers, 2017 to 2023). "The most common 44 genes (p<0.001) including VHL enlist MON1A, CCDC51 and TMA7 at 3p21.31 (31/29 HRO tumours), and MIRLET7G and WDR28 at 3p21.1 (31/31 tumours), respectively." (PMID 28486536, 2017).
TMA7 also shares sentences with these, for which no sentence is quoted: Diabetes (1 paper); Obesity (1).